IFI16 (interferon gamma inducible protein 16)
Diseases named in the same sentence as IFI16 in open-access papers (continued):
Sharing a sentence is not in itself a finding about the gene and the disease.
Listeria monocytogenes infection (4 papers, 2017 to 2022). "Specifically, human IFI16 was shown to amplify the cGAS-STING canonical pathway to induce IFNβ in response to Listeria monocytogenes infection and the subsequent presence of bacterial DNA in the cytosol of human macrophages." (PMID 32922386, 2020). "Indeed, Listeria infection led to increased expression of both IFI16 and IFN-β in WT macrophages carrying CD44." (PMID 30540779, 2018). "In vertebrates, STING has been reported to be triggered by bacterial DNA-activated cGAS or another DNA sensor, IFI16, leading to the production of IFN-I during Listeria monocytogenes infection." (PMID 36059529, 2022).
acute myeloid leukemia (3 papers, 2022 to 2025). Acute myeloid leukemia (AML) is a group of neoplasms arising from precursor cells committed to the myeloid cell-line differentiation. "Conversely, in acute myeloid leukemia (AML) cell lines, curcumin has been found to activate the NLRC4, AIM2, and IFI16 inflammasomes, inducing pyroptosis through the upregulation of the ISG3 transcription factor." (PMID 40725015, 2025). "In models of acute myeloid leukemia (AML), curcumin appears to operate through a non-canonical inflammasome pathway by upregulating interferon-stimulated gene ISG3, thereby activating NLRC4, AIM2, and IFI16 inflammasome sensors." (PMID 40806716, 2025).
asthma (3 papers, 2013 to 2025). "We stained cadaveric lung tissue from 4 healthy individuals and 4 patients who had fatal asthma for IFI16 and p-STING." (PMID 40526428, 2025). "The overall expression of IFI16 was increased in fatal asthma." (PMID 40526428, 2025). "In contrast, IFI16 was mostly extranuclear and cytosolic in fatal asthma." (PMID 40526428, 2025). "Human epithelial cells from patients with asthma stimulated in vitro with RV‐A16 showed an upregulation of genes involved in DNA‐sensing and STING pathway such as the DNA sensors ZBP1, IFI16 and the cytosolic TRIM21." (PMID 39466641, 2025).
atherosclerosis (3 papers, 2014 to 2025). A disease characterized by the build-up of fatty material and calcium deposition in the arterial wall resulting in partial or complete occlusion of the arterial lumen. "Metformin's ability to inhibit cell proliferation and migration of human aortic SMCs is diminished when IFI16 is silenced, indicating IFI16's protective role against vascular remodeling and atherosclerosis." (PMID 39158380, 2025). "This review delves into the complex interplay between IFI16 and PANoptosis in heart diseases, including atherosclerosis, myocardial infarction, heart failure, and diabetic cardiomyopathy." (PMID 38693141, 2024). "AIM2 and IFI16 have also shown the other same features, such as cytosolic dsDNA sensors, ASC (apoptosis-associated speck-like protein containing a CARD)-dependent inflammasomes, regulating atherosclerosis, autoimmunity, tumorigenesis, and normal neuronal development." (PMID 38693141, 2024). "This intricate connection suggests that targeting the IFI16-STING-IRF3 pathway and its associated PANoptosis mechanisms could offer novel therapeutic strategies for managing cardiometabolic diseases that have an inflammatory component, such as atherosclerosis." (PMID 38693141, 2024). "This is not the case for GBP5, Ubd, SectM1, Ifi16, Upp1 and Fam26F, and could therefore represent potential novel biomarkers of atherosclerosis." (PMID 25478796, 2014).
autism (3 papers, 2014 to 2024). Persistent deficits in social interaction and communication and interaction as well as a markedly restricted repertoire of activity and interest as well as repetitive patterns of behavior. "Particularly, IFI16 (interferon, gamma-inducible protein 16), an anti-inflammatory and innate antiviral gene, is decreased in the blood cells of infants and toddlers at risk for autism, but it is increased in the plasma of patients with autism." (PMID 38994948, 2024). "In contrast to BDNF and IL6, we observed decreased expression of IFI16, an anti-inflammatory gene, in the NSCs of patients with autism." (PMID 38994948, 2024). "This is in line with other studies reporting increased levels of IFI16 in plasma and its hyper-expression in the brain of patients with autism patients." (PMID 38994948, 2024). "GABA, oxytocin, and IFI16 can be used as biochemical correlates to social and cognitive impairment in autism." (PMID 24400970, 2014). "Levels of glutamate, GABA, glutamate/GABA, TNF-α, IL-6, IFN-γ and IFI16 were compared between patients with autism and age-matched control subjects." (PMID 25407263, 2014). "The relationship between the selected parameters confirms the role of impaired neurochemistry and neuro-inflammation in the etiology of autism spectrum disorders and the possibility of using GABA, oxytocin, and IFI16 as markers of autism severity." (PMID 24400970, 2014). "Levels of GABA, serotonin, dopamine, oxytocin, and IFI16 were compared between patients with different severity of autism (mild-moderate or severe) and age-matched control subjects." (PMID 24400970, 2014). "Regarding IFI16, an anti-inflammatory gene, we found a highly significantly reduced expression in the NSCs (75%) but a significantly increased expression in the astrocytes (>45%) of patients with autism vs. controls." (PMID 38994948, 2024). "Regarding anti-inflammatory genes, while IFI16 expression was significantly decreased in the NSCs of patients with autism (p = 0.005), its expression was increased in astrocytes (~50%, p = 0.02) and only insignificantly in the neurons of patients with autism." (PMID 38994948, 2024). "Therefore, astrocytes might be the origin of an overall higher IFI16 expression in the brains of patients with autism." (PMID 38994948, 2024). "In postmortem brain samples, we found DNA hypomethylation of TGFB2 and IFI16 promoter regions, but DNA hypermethylation of HAP1 and SLC1A2 promoters in autism." (PMID 38994948, 2024). "However, after differentiation, IFI16 exhibited significant up-regulation in the astrocytes, whereas IL6 was upregulated in both astrocytes and neurons of patients with autism." (PMID 38994948, 2024). "The remarkable elevation of IFI16 in Saudi individuals with autism as subjects of the present study could be supported through consideration of the recent work of El-Ansary and Al-Ayadhi, in which they recorded high significant increases of IFN-γ as inducer to IFI16." (PMID 24400970, 2014). "In addition, the significant positive correlation between IFI16 and GABA together with the negative correlations between this inflammatory marker and serotonin, dopamine, and oxytocin can support the role of inflammation in the neurochemical dysregulation recorded in patients with autism." (PMID 24400970, 2014).
fibrosis (3 papers, 2018 to 2025). the formation of excess fibrous connective tissue in an organ or tissue in a reparative or reactive process. "Following the observation that DDR inhibition with NU7441 improved cardiac function and reduced IFI16 levels in vivo, we further investigated the effects of targeting the DDR pathway and IFI16 on cardiac fibrosis and injury markers." (PMID 40365289, 2025). "Only IFI16 was upregulated in both IPF and liver cirrhosis, indicating that it was universally activated in fibrosis." (PMID 39257588, 2024). "Researches show that chronic liver inflammation may lead to fibrosis and cirrhosis through IL-1signaling.And IFI16 can stimulate cleavage of pro-IL1b and pro-IL18 to the bioactive cytokines.So IFI16 may play a role in the pathogenesis of liver cirrhosis, next step we can further investigate it." (PMID 29743020, 2018).
glioma (3 papers, 2022 to 2025). A benign or malignant brain and spinal cord tumor that arises from glial cells (astrocytes, oligodendrocytes, ependymal cells). "This analysis confirmed significantly upregulation of LRGs score and its core genes (KIF2C, CALD1, HSPE1, and IFI16) in glioma versus normal tissues." (PMID 41035644, 2025). "TRIM21-mediated degradation of interferon gamma inducible protein 16 (IFI16) and hu-antigen R (HuR) inhibits radiation therapy resistance in stemness of gliomas." (PMID 39154024, 2024).
head and neck squamous cell carcinoma (3 papers, 2009 to 2025). A squamous cell carcinoma that arises from any of the following anatomic sites: lip and oral cavity, nasal cavity, paranasal sinuses, pharynx, larynx, and salivary glands. "Restoration of IFI16 levels in head and neck squamous cell carcinoma (HNSCC) exhibits potent antitumor effects by inhibiting tumor growth and in vitro transforming activity, as well as augmenting doxorubicin-induced cell death via the accumulation of cells at the G2/M phase." (PMID 40386782, 2025).
Hepatitis (3 papers, 2018 to 2024). Inflammation of the liver. "Upregulated ISGs (ISG20, IFI16, TAP2, GBP1, PSMB9) in the hepatitis phase were associated with T cell and macrophage infiltration and positively correlated with ALT levels." (PMID 39135698, 2024). "Furthermore, intrahepatic IFI16 expression gradually increased in accord with elevations in the grade of liver inflammation." (PMID 29743020, 2018). "In recent years, the role of IFI16 in RNA virus infections has been identified, whereby IFI16 transcriptionally upregulates the gene expression of IFN-I in Sendai virus (SeV) and mouse hepatitis coronavirus infection." (PMID 35906635, 2022). "Conversely, other ISGs, including ISG20, IFI16, APOBEC3G, CXCL10, and CXCL11, which were predominantly expressed in T cells and nMacs, and upregulated during the hepatitis phase, showed a positive correlation with serum ALT levels, indicating their involvement in liver injury." (PMID 39135698, 2024).
hepatitis B virus infection (3 papers, 2021 to 2024). A viral infection caused by the hepatitis B virus. "Besides NLRP3 inflammasome, IFI16 and AIM2 inflammasomes participate in the pathological process of hepatitis B, and NALP3 inflammasome may sense HCV infection in hepatocytes." (PMID 38817443, 2024).
lupus nephritis (3 papers, 2022 to 2024). Glomerulonephritis in the context of systemic lupus erythematosus. "Autoantibodies against IFI16 have been identified in people with SLE, and a recent study showed that expression of IFI16 was associated with SLEDAI and prognosis in lupus nephritis." (PMID 39696438, 2024). "Here, we demonstrate for the first time that the DNA sensors AIM2 and IFI16 bind to NETs in vivo, through imaging studies of proliferative lupus nephritis specimens." (PMID 35608258, 2022). "Importantly, IFI16 expression is significantly greater in kidneys of patients with lupus nephritis than in those of patients with various kidney diseases, such as minimal change disease, IgA nephropathy, and diabetic kidney disease." (PMID 39478861, 2024).
lymph node metastasis (3 papers, 2021 to 2025). "In this study, typical prognostic factors, tumor invasion and lymph node metastasis, were positively correlated with a high expression of IFI16 in resected ESCC samples." (PMID 37998338, 2023). "Next, we evaluated the relationship between expression levels of IFI16 and clinical-pathological parameters (lymph node metastasis, stage, and grade) in ccRCC patients: IFI16 was highly expressed in ccRCC patients with lymph node metastasis, higher tumor stages, and higher histopathological grades." (PMID 33659024, 2021). "The phenotypic expression characterized by IFI16 negativity combined with Ki-67 positivity (IFI16-/Ki-67+) has been notably and positively correlated with advanced TNM staging in cancer patients, and it exhibits a borderline significant link to lymph node metastasis, as reported in a pivotal study." (PMID 40386782, 2025).
medullary thyroid carcinoma (3 papers, 2010 to 2019). "Interestingly, a relationship between STAT3 activation and IFI16 expression during cell apoptosis was detected in medullary thyroid carcinoma and mammary epithelial cells." (PMID 26185770, 2015). "Additionally, over-expression of IFI16 protein in medullary thyroid carcinoma cells significantly down-regulated the expression of the E2F1, a transcriptional repression target of the pRb-E2F repressor complex." (PMID 20052289, 2010).
oral cancer (3 papers, 2021 to 2025). "Search terms included combinations of “inflammasome,” “NLRP3,” “AIM2,” “IFI16,” “dental pulp,” “pulpitis,” “periodontitis,” “chronic oral inflammation,” “interleukin-1β,” “interleukin-18,” “oral squamous cell carcinoma,” “oral cancer,” “NF-κB,” “bacterial pathogens,” and related terms." (PMID 41440367, 2025). "However, a controversial argument of the role of IFI16 in cancer was found in both oral cancer and renal clear cell carcinoma, in which IFI16 may serve as an oncogene to promote cell proliferation and tumor progression." (PMID 34150748, 2021).
renal carcinoma (3 papers, 2021). A carcinoma arising from the epithelium of the renal parenchyma or the renal pelvis. "For example, bioinformatic studies have confirmed that IFI16 is a valuable prognostic marker and a promising therapeutic target in renal carcinoma." (PMID 34930258, 2021). "On a similar note, a significant association between the expression of ELK4, CBFB, IFI16, PRRX1, AEBP1, and GATA3 with an unfavourable outcome in renal cancer has been identified in previous reports." (PMID 35201514, 2021). "The CCK-8 analysis suggested that knocking down IFI16 expression in the renal cancer cell line inhibits the proliferation of RCC cells." (PMID 33659024, 2021). "For instance, ELK4, CBFB, IFI16, PRRX1, AEBP1, and GATA3 expression was associated with an unfavourable outcome in renal cancer revealing the significance of these TFs (pink and blue colours represent unfavourable and favourable prognosis, respectively)." (PMID 35201514, 2021).
Sepsis (3 papers, 2021 to 2025). Sepsis is defined as life-threatening organ dysfunction caused by a dysregulated host response to infection. "This review builds upon prior work highlighting NLRP3 as a master regulator of inflammatory signaling in sepsis, while extending current understanding by addressing lesser-explored sensors like AIM2 and IFI16." (PMID 40558557, 2025). "In the GSE64456 control and sepsis groups, LYN (tyrosine protein kinase Lyn), and IFI16 (interferon gamma-inducible protein 16) had degree 56 and 70, respectively." (PMID 33667236, 2021).
breast tumor (2 papers, 2017 to 2022). "Taken together, these findings demonstrate that elevated levels of type I IFNs in the breast tumor microenvironment led to IFI16-mediated aromatase activation and E2 production in adipose tissue surrounding BC, supporting the E2-dependent growth of ER-positive BC cells." (PMID 35593921, 2022).
Cirrhosis (2 papers, 2006 to 2018). A chronic disorder of the liver in which liver tissue becomes scarred and is partially replaced by regenerative nodules and fibrotic tissue resulting in loss of liver function. "Second, other diseases that occur during the progression of HBV infection, including cirrhosis, should be included to explore the comprehensive role of IFI16 in the complete progression of HBV infection." (PMID 29743020, 2018). "A small set of genes (ISG20, IFI16, TRIM22, STAT5A) were also highly up-regulated in nearly all samples, including ethanol-cirrhotic livers, suggesting these may play a role in an inflammatory response related to cirrhosis development regardless of etiology." (PMID 17121680, 2006).
colon cancer (2 papers, 2011 to 2016). "In this context, it is interesting to note that the loss of IFI16 expression in human colon cancer cell lines is associated with KRAS mutations." (PMID 21573174, 2011).
corneal infection (2 papers, 2019 to 2021). A viral or bacterial infectious process affecting the cornea. "Prior studies found that corneal infection of NLRP3-/- mice results in more severe immunopathogenesis, and that corneal HSV-1 infection induces the NLRP3, NLRP12, and IFI16 inflammasomes." (PMID 33524073, 2021). "Since induction of inflammasomes triggers Caspase-1 activation, we next determined whether corneal infection with virulent HSV-1 strains would enhance the expression levels of one or several of the five major inflammasomes: NLRP3, NLRP6, NLRP12, IFI16/p204, and AIM2." (PMID 31367214, 2019).
liver cancer (2 papers, 2020 to 2021). An epithelial or non-epithelial malignant neoplasm that arises from the liver. "Forced expression of IFI16 in liver cancer cells reduced cell viability and promoted apoptosis, and overexpression of IFI16 inhibited the proliferation of liver cancer cells and reduced the size of tumors." (PMID 33659024, 2021). "In our study, we found that NLRC3 and IFI16 were independent prognostic factors for favorable OS in patients with liver cancer." (PMID 33006365, 2020).
lung disease (2 papers, 2018 to 2024). "The majority of RA patients with detectable circulating IFI16 protein were also positive for RF/ACPA, and the presence of circulating IFI16 protein was significantly associated with RA-associated lung disease." (PMID 39450183, 2024).
lung fibrosis (2 papers, 2020 to 2024). "One of the core DEGs, IFI16, might also play certain roles in lung fibrosis as suggested by its upregulation in IPF." (PMID 39257588, 2024).
nephritis (2 papers, 2018). Inflammation of renal tissue. "In the specific case of SLE, anti-IFI16 antibodies had an inverse correlation to proteinuria and C3 hypocomplementaemia suggesting that actual actions of the unblocked IFI16 could play a role in nephritis." (PMID 30116756, 2018).
ovarian carcinoma (2 papers, 2017 to 2022). A malignant neoplasm originating from the surface ovarian epithelium. "In contrast, in ovarian cancer cells, IFI16 appeared to be involved in drug resistance." (PMID 28611294, 2017). "Our results also indicate that protein expression of IFI16 could differ in histologically different types of ovarian cancer." (PMID 28611294, 2017). "Thus, the role of IFI16 in cancers may be cancer-type specific; however, in ovarian cancer cells, its overexpression appears to be related to the drug-resistant phenotype." (PMID 28611294, 2017). "The expression of EPHA7, IFI16, SPP1 and TGFBI was confirmed at protein level in analyzed ovarian cancer patients.." (PMID 28611294, 2017).
pancreatic adenocarcinoma (2 papers, 2023 to 2025). "A high expression of IFI16 in tumors has been significantly associated with poor overall survival in pancreatic adenocarcinoma and RCC." (PMID 37998338, 2023).
pancreatic cancer (2 papers, 2022 to 2023). "A previous report demonstrated that the transplantation of a pancreatic cancer cell line overexpressing IFI16 into mice promoted TAM infiltration, which in turn promoted tumor growth." (PMID 37998338, 2023). "Interferon-inducible protein 16 (IFI-16) is increased in pancreatic cancer, and elevated IFI-16 correlates to a poor prognosis." (PMID 35739593, 2022). "Overexpression of IFI-16 in pancreatic cancer cells induces the maturation, infiltration, and proliferation of TAM in the tumor microenvironment by activating inflammasomes and therefore increasing the release of IL-1β." (PMID 35739593, 2022).
periodontal disease (2 papers, 2020). "Thus, understanding how variants of IFI16 and AIM2 contribute to periodontal disease pathogenesis may lead to treatment options that address individual biological variations and precision therapies for oral health." (PMID 32533779, 2020). "There are limited data exploring the role of IFI16 and AIM2 in periodontal disease pathogenesis." (PMID 31850638, 2020). "We identified polymorphisms in inflammasome genes interferon gamma inducible protein 16 (IFI16) and absent in melanoma 2 (AIM2) that were associated with increased severity of periodontal disease." (PMID 32533779, 2020). "Until the GWAS finding, IFI16 had never been explored in the context of periodontal disease." (PMID 32533779, 2020).